S100A10 (S100 calcium binding protein A10)
Diseases named in the same sentence as S100A10 in open-access papers (continued):
Sharing a sentence is not in itself a finding about the gene and the disease.
tumor (101 papers, 2007 to 2026). "S100P is overexpressed in multiple cancers and linked to poor prognosis in LUAD, while S100A10 contributes to membrane repair and drug resistance in tumor progression." (PMID 40433361, 2025). "In contrast, deficiencies in the plasminogen receptors Plg‐RKT or S100A10 in tumor cells significantly reduced tumor growth." (PMID 37971174, 2024). "Reduced tumor growth was linked to reduced macrophage infiltration to the tumors secondary to loss of S100A10 expression by the macrophages." (PMID 37971174, 2024). "S100A10 overexpression is commonly reported in various malignancies and is closely associated with tumor cell characteristics and prognosis." (PMID 37781076, 2023). "In PDAC, S100A10 has been reported to be not only up-regulated in tumor tissues but also associated with survival outcomes." (PMID 36612197, 2022). "S100A10 is responsible for nearly 50% of cellular plasmin generation and controls cancer cell invasion and metastasis as well as recruits tumor-associated cells to the tumor site." (PMID 36430822, 2022). "It has been reported that S100A10 plays a key regulatory role of toll-like receptors that can activate the innate immune system and are associated with tumor growth." (PMID 36430822, 2022). "In the Lewis lung carcinoma (LLC) mouse model, deficiency in S100A10 reduced macrophage recruitment to the tumor site." (PMID 34209679, 2021). "Human CRC tissues were used to evaluate the association between S100A10 expression level, tumor differentiation, and lymph node metastatic foci (-a, -b, c)." (PMID 34336846, 2021). "The Annexin A2 (ANXA2)-S100A10 heterotetramer is an important plasminogen receptor, associated with tumor invasion and metastasis." (PMID 32867190, 2020). "The results showed that increased expression of S100A10 was positively associated with carboplatin resistance (P < 0.001), tumor grade (P = 0.048) and a poorer prognosis (P = 0.0053)." (PMID 31739800, 2019). "Taken together, these results suggest that S100A10 is overexpressed in GC tissues and metastatic lymph nodes associated with an aggressive tumour phenotype." (PMID 30394687, 2019). "Our previous findings show that LLC cells yield dramatically smaller tumors in S100A10‐null mice compared to wild‐type mice and that both tumoral microenvironment and tumor‐associated macrophages were essential for sustaining tumor growth." (PMID 30009399, 2018). "Research showed that S100A10 was selectively translocated to matrix vesicles of Saos-2 cells upon mineralization, whereas, in the context of cancer, S100A10 was shown to be linked to tumor progression." (PMID 40358151, 2025). "In addition, the overexpression of S100A10 is related to tumour progression, and the quantitative polymerase chain reaction (PCR) confirmed that S100A10 is associated with the malignant transformation of kidney cells." (PMID 38213532, 2023). "Accordingly, S100A10 upregulation may be linked to immune cell infiltration in a manner conducive to tumor immune evasion." (PMID 37781076, 2023). "Several documents indicate that this may be due to the impact of S100A10 on the apoptotic activity of Bcl-xL/Bcl-2 associated death promoter (BAD) for tumor cells." (PMID 31949486, 2020). "Interestingly, S100A10 expression on tumor-associated macrophages (TAMs) is required for their recruitment to primary tumor sites in a lewis lung carcinoma (LLC) mouse model." (PMID 23519104, 2013). "As our data unprecedently reveal potential hepatoprotective role for endogenous S100A10, we then over-expressed S100A10, and assessed tumor initiation and cancer progression." (PMID 40841353, 2025). "Several S100 proteins show differential expression in BC tissues compared to normal urothelium, suggesting their potential roles in tumor progression, metastasis, and prognosis.S100C (also known as S100A10) is notably downregulated during BC progression." (PMID 41404073, 2025).
tumor (continued). "In order to identify possible oncogenes/drivers (ONC/D) or tumor suppressors (TS) modulated specifically by S100A10 or S100A11, we processed the proteomic data using CancerMine database." (PMID 40841353, 2025). "S100A10 has been shown to mediate the migration of macrophages towards tumour sites and contribute to MAPK and NF-κB induction of inflammatory cytokines." (PMID 39510801, 2025). "If this accumulation drives the tumor suppressive properties of S100A10 remains unexplored and requires further investigations." (PMID 40841353, 2025). "Based on both the DEN/DEN-HFD and the LPTENKO models, we identified a crucial protective role for S100A10 on tumoral initiation, in MASLD setting, whereas S100A11 favors growth of tumors in two out of 3 models analyzed." (PMID 40841353, 2025). "Whereas the absence of fibrin(ogen) did not significantly influence tumor growth and had only a modest impact on metastasis, expression of Plgrkt or S100a10 by the tumor cells significantly enhanced both primary tumor growth metastatic potential." (PMID 37971174, 2024). "The results indicate that compared to the S100A10-sh-NC group, the tumor decreased in size, and the growth rate of MHCC97-L cells within the NOD-SCID mice decreased in the S100A10-sh group." (PMID 39117605, 2024). "A significant reduction in KPC primary tumor growth and metastatic potential following reduction of Plgrkt expression and S100a10 in KPC tumor cells using shRNA was observed." (PMID 37971174, 2024). "The Western blot results showed that compared to the S100A10-sh-NC group, the phosphorylation level of cPLA2 protein in the tumor tissue of the S100A10-sh group was significantly reduced, but there was no significant change in the protein content of 5-LOX." (PMID 39117605, 2024). "HPLC results showed that compared with the S100A10-sh-NC group, the content of LTB4 in tumor tissues was significantly decreased in the S100A10-sh group." (PMID 39117605, 2024). "The reduction in KPC tumor growth with suppression of Plgrkt or S100a10 expression in the tumor cell is consistent with low tumor expression of these genes in human PDAC being associated with prolonged patient survival." (PMID 37971174, 2024). "Plasmin engages tumor cell receptors Plgrkt and S100A10:annexin A2 to enhance tumor growth and metastasis." (PMID 37971174, 2024). "Here, S100A10 expression was found to be negatively correlated with tumor infiltration by T cells, NK CD56bright cells, pDC, Eosinophils, CD8 T cells, Mast cells, B cells, NK cells, TFH cells, T helper cells, and Tem cells." (PMID 37781076, 2023). "In contrast, S100A10 levels were unrelated to patient age, or to the tumor T, N, M, G, or clinical stages (P > 0.05)." (PMID 37781076, 2023). "In this study, S100A10 overexpression was observed in CESC tumor samples in comparison with healthy tissues, and these findings were corroborated in a separate cohort of clinical samples." (PMID 37781076, 2023). "The area under the curve for S100A10 when diagnosing CESC was 0.935, and S100A10 was found to regulate tumor cell proliferation and metastasis both in vitro and in vivo." (PMID 37781076, 2023). "CPT1A regulates the expression and stability of its substrate proteins, such as S100A10 and enolase 1, through CPTase-independent lysine succinyltransferase activity, thereby promoting tumor cell growth, proliferation and migration." (PMID 37291333, 2023). "S100A10 is involved in macrophage infiltration into tumor tissues, development of drug resistance by tumor cells during clinical chemotherapy, and invasion and metastasis of malignant tumors." (PMID 37533434, 2023). "Next, we used the TIMER database to analyze the correlation between the expression of S100A10 and tumor purity and the infiltration of CD8 + T cells, CD4 + T cells, B cells, dendritic cells, macrophages and neutrophils." (PMID 37420211, 2023).
tumor (continued). "Among them, 39 patients showed high expression levels of S100A10 protein in tumor tissues, and 40 patients showed low expression levels of S100A10 protein in para cancer tissues." (PMID 37420211, 2023). "The Ras oncogene is also a major driver of many cancers, and S100A10 interactions with Ras can reportedly enhance tumor cell invasivity through basement membrane and extracellular matrix degradation." (PMID 37781076, 2023). "S100A10, a member of the S100 protein family, is upregulated in multiple human malignancies and plays a key role in regulating tumor progression." (PMID 37476183, 2023). "Subsequently, qRT-PCR was used to detect the expression level of S100A10 mRNA in tumor tissues and para cancer tissues of these 40 patients." (PMID 37420211, 2023). "Several recent studies have suggested that S100a10 is a critical gene for cancer cell migration, as well as the tumor-promoted macrophage migration; however, its role in monocyte–macrophage differentiation has not been reported." (PMID 37426471, 2023). "the results showed that S100A10 was related to tumor immune cell infiltration in many types of cancers including HCC." (PMID 37420211, 2023). "S100A10 has been reported to promote tumor progression and metastasis by regulating multiple signaling pathways related to cell migration, invasion, metastasis, and angiogenesis." (PMID 36612197, 2022). "Mice-bearing orthotopic pancreatic tumors showed that S100A10 knocked-down PANC-1 cells had a smaller tumor size than the control group." (PMID 36612197, 2022). "In vascular co-option areas, we expected to observe P-gp- or S100A10-positive tumor cells surrounding blood vessels with reduced CD31, P-gp, and mitochondria expression." (PMID 36553127, 2022). "Furthermore, SUMO1-modified S100A10 can translocate into nuclei to up-regulate the expression of genes associated with actin dynamics and cytoskeleton remodeling, followed by the enhanced migration capacity of polyploid tumor giant cells and their daughter cells." (PMID 36612197, 2022). "The differences in S100A10/CD31 co-expression were insignificant in the two methods of tumor growth." (PMID 36553127, 2022). "Switched memory B cells, characterized by expression of S100A10, a negative regulator of Toll-like receptor function, were reduced in tumor tissue whilst plasmablast populations were increased." (PMID 36253784, 2022). "SUMOylation promoted the nuclear localization of S100A10 in polyploid tumor giant cells and their daughter cells for stimulating the proliferation and migration of cells." (PMID 35864967, 2022). "We proposed that S100A10-dependent plasmin generation plays a critical role in the movement of macrophages to the tumor site and, therefore, S100A10 was essential and sufficient for macrophage migration to tumor sites." (PMID 34944416, 2021). "We observed a dramatic delay in tumor onset, growth, and progression to malignancy in the PyMT/S100A10 knockout mice." (PMID 34944416, 2021). "The movement of these macrophages to the tumor site is dependent on proteolytic activity, and several plasminogen receptors, including enolase, histone H2B, Plg-RKT, and S100A10, have been shown to play a role in macrophage recruitment to the tumor site." (PMID 34944416, 2021). "In vivo tumor growth assays showed that S100A10-overexpressing Hep3B cells had a larger tumor size than control." (PMID 34178044, 2021). "We further discuss the evidence derived from animal models supporting the role of S100A10 in tumor progression and oncogenesis." (PMID 34944416, 2021). "Previous studies have shown that the overexpression of S100A10 is usually related to tumor size, pathological TNM stage, lymphovascular invasion, lymph node metastasis, poor prognosis, and drug resistance in many malignancies." (PMID 34804125, 2021). "The loss in tumor development was caused, in part, by the requirement for the recruitment of macrophages to the tumor site, an event mediated by S100A10." (PMID 34944416, 2021).
tumor (continued). "In our study, the results showed that the expression of S100A10 was significantly upregulated in HCC tissues than in para-tumor tissues." (PMID 33815482, 2021). "The gene expression profile analysis demonstrated that the levels of S100A4/S100A6/S100A10/S100A11/S100A13/S100P were higher in tumor than in normal liver samples." (PMID 33815482, 2021). "S100A10 expressed on the surface of macrophages plays an important role in the interaction with tumor microenvironment and tumor growth." (PMID 34804125, 2021). "This suggested that the involvement of S100A10 in tumor initiation was complex and involved more than a single step of oncogenesis." (PMID 34944416, 2021). "S100A10 has been shown to be present on the surface of macrophages 52 and plays important roles in tumor progression induced by TAMs." (PMID 31949486, 2020). "Among the signature genes we researched, HSPA4, FABP6, S100A10, CACYBP, SHC1 and HDAC1 were associated with a higher tumor grade, CACYBP was linked with a higher clinical stage as well as T stage." (PMID 32191631, 2020). "S100A10 activated the mTOR pathway by interacting with annexin A2 (ANXA2) to accelerate tumor glycolysis, resulting in tumor malignant progression." (PMID 33324631, 2020). "In most cases, S100A10 positively regulates the tumor progression through plasmin production and fibrin barrier degradation." (PMID 31949486, 2020). "In both cases, a membranous positivity for S100A10 was diffusely found in both tumor buds and PDCs and was observed in the tumor cells protruding toward the stroma, giving rise to TB/PDC." (PMID 33160379, 2020). "S100A10 was known to be involved in the regulation of various malignant tumors and non-tumor diseases." (PMID 31949486, 2020). "Breast cancer, for instance, is positively regulated by S100A10 and its target protein Annexin A2 in the migration of its tumor cells." (PMID 31949486, 2020). "S100A10 participates in both invasion and metastasis of tumor cells by activating proteases, such as plasmin, MMP-2, MMP-9, as well as their receptors." (PMID 31949486, 2020). "S100A10 is important in promoting tumor malignant growth in ovarian cancer, colorectal cancer, lung cancer, and pancreatic ductal carcinoma." (PMID 33324631, 2020). "Knockdown of S100A10 expression suppresses the activation of the mTOR pathway, thus inhibiting glycolysis and tumor growth." (PMID 33324631, 2020). "Here, this review systematically summarizes the structure and functions of S100A10 and its significant role in the modulation of malignant tumor and non-tumor diseases." (PMID 31949486, 2020). "Considerable attention should be paid to understand the significant role of S100A10 in the modulation of malignant tumor and non-tumor diseases." (PMID 31949486, 2020). "A xenograft tumor model was established to confirm the role of S100A10 in carboplatin resistance in vivo." (PMID 31739800, 2019). "High S100A10 expression levels at age < 60 at diagnosis and tumor grade G3 were significantly higher than those at age ≥ 60 at diagnosis." (PMID 31739800, 2019). "Consistent with this, there was a significant increase in the steady‐state levels of total S100A10 protein in tumour tissues compared to levels in normal gastric tissues." (PMID 30394687, 2019). "Compared with the control, knockdown of S100A10 significantly inhibited tumor growth and showed a marked decrease in tumor weight." (PMID 31739800, 2019). "Taken together, these data indicate that S100A10 K47 succinylation promotes tumour cell invasion and metastasis." (PMID 30394687, 2019). "A recent study reported that S100A10 is required for tumor-promoting macrophage migration to tumor sites." (PMID 31739800, 2019). "Results showed that lysine succinylation of S100A10 was more prevalent in tumour tissues than in normal tissues." (PMID 30394687, 2019). "Collectively, both mRNA and protein levels of S100A10 revealed a similar trend of upregulation in tumor tissue compared to normal tissue." (PMID 30009399, 2018).
tumor (continued). "S100A10 also plays a critical role in the migration of macrophages to tumor sites and is reported to be a rate-limiting step that controls tumor progression." (PMID 30572596, 2018). "We compared S100A10 mRNA expression in normal and tumor samples from previously published DNA microarray and RNA seq expression datasets." (PMID 30009399, 2018). "Collectively, these studies establish a pro-tumorigenic role for S100A10 as a key contributor in plasmin regulation, tumor progression, and metastasis." (PMID 30572596, 2018). "S100A10 specifically binds to plasminogen, and plasminogen activation is a key step in tumor growth and invasion." (PMID 29324674, 2018). "Six probes met the criteria of 1) being differentially hypomethylated in tumor tissue compared to normal tissue and 2) negatively correlated with S100A10 mRNA expression." (PMID 30009399, 2018). "Our findings indicated that S100A10 contributes to tumor cell proliferation potentially via sustenance of CCND1 levels and to angiogenesis by maintaining VEGF production to ensure blood vessel development." (PMID 30009399, 2018). "Tumor growth was reduced in S100A10-null mice, compared with wild-type mice, and was accompanied by less macrophages within the tumor." (PMID 29379499, 2017). "In particular, many studies suggest that annexin A2-mediated tumor cell invasiveness is attributable to the generation of extracellular plasmin through modulation of S100A10 enzyme activity." (PMID 28652618, 2017). "There were many macrophages throughout the tumor in wild-type mice, where macrophages were observed only around the absolute tumor tissue border in S100A10-null mice." (PMID 29379499, 2017). "S100A10 is overexpressed in animal tumor model systems and in human cancer, where it correlates with a poor prognosis and chemotherapeutic resistance." (PMID 27351226, 2016). "In various animal tumor model systems, the inhibition of S100A10 expression, or activity, decreases tumor growth and metastasis." (PMID 27351226, 2016). "Meghnani and colleagues also reported an up‐regulation of the RAGE ligands S100B, S100A2, S100A4, S100A6 and S100A10 in RAGE overexpressing tumours." (PMID 26928771, 2016). "S100A10 has also attracted considerable attention for its role as an essential molecule in tumor progression via macrophage migration to tumor sites." (PMID 24851084, 2014). "S100A10 plays a role in oncogenesis by regulating the plasmin proteolytic activity of cancer cells and by regulating the migration of macrophages to the tumor site." (PMID 24604026, 2014). "S100A10 is a plasminogen receptor and this has been suggested as being a promoter of angiogenesis and tumor metastasis." (PMID 23166536, 2012). "We reported DLC1 interaction with S100A10, an inflammatory protein and a key cell surface receptor for plasminogen that regulates pericellular proteolysis and tumor cell invasion." (PMID 22580498, 2012). "S100A10 has been identified as a plasminogen receptor, suggesting its promotion of angiogenesis and tumor metastasis." (PMID 22206547, 2011). "S100A10 was hypermethylated in four tumours (11.4%) and seven cell lines (78%), relative to the normal cerebellum." (PMID 17579622, 2007). "Based on these data, preventive S100A10 over-expression restrains tumor growth and might protect against liver tumor incidence." (PMID 40841353, 2025). "As we demonstrate an aggravation of hepatocarcinogenesis upon S100A10 downregulation, we can argue that its overexpression may act as a tumor suppressive mechanism of the cell to restrain tumor development." (PMID 40841353, 2025). "Building on our network result that key gene set 2 is enriched for mitochondrial energy metabolism, the late-stage regulators we identified—UQCR11, NDUFB4, PRDX3, and S100A10—map to pathways that could support or amplify ADSCs-to-tumor bioenergetic coupling." (PMID 41325391, 2025).